TNF (tumor necrosis factor)
Diseases named in the same sentence as TNF in open-access papers (continued):
Sharing a sentence is not in itself a finding about the gene and the disease.
cancer (continued). "Among the targets, 22 genes were involved in cancer, apoptosis, and TNF signaling pathways, all of which are related to the immune response." (PMID 32182890, 2020). "The TNF-α-induced pro-survival function of NF-κΒ in cancer cells is recognized as a main feature in most human cancers." (PMID 32231206, 2020). "Systemic toxicity still prevents full clinical application of cytokines such as TNF and interferons (IFNs), which hold great potential for cancer immunotherapy." (PMID 31912630, 2020). "In 2008, The Food and Drug Administration (FDA) released investigatory reports of malignancy in children receiving anti-TNF agents for immune-related diseases including IBD." (PMID 32903330, 2020). "Almost half of the patients who developed a form of cancer (four out of nine) had received immunosuppressants or anti-TNF medications." (PMID 32842528, 2020). "Other factors such as tumor necrosis factor (TNF)-α, IL-1, IL-6, colony stimulating factor (CSF)-1, IL-8, IL-10, and type 1 interferons (INFs) can also contribute to cancer growth." (PMID 32695118, 2020). "TNF plays a dual role in cancer immunity, TNF induced T-cell adhesion is ICAM1 and VCAM1 dependent, and most of the chemo-attracted cells are Tregs, Bregs and MDSC, which are negative modulators of the immune response." (PMID 33381115, 2020). "The pathway enrichment analysis (KEGG) revealed lysosome, phagosome, antigen processing and presentation, TNF-signal pathway, transcriptional mis-regulation in cancer, and cell adhesion molecules." (PMID 33013913, 2020). "The NF-κB and TNF-α signaling pathways are crucial elements in inflammation and tumorigenesis, as well as cancer cell proliferation and metastasis." (PMID 32317702, 2020). "Cancer cell invasion has been shown to be promoted by TNFα via MMP-9 expression, thus activating EMT." (PMID 32751717, 2020). "The expression levels of TNF-α and TGF-β receptors were also found upregulated in cancer-associated mesothelial cells compared with normal mesothelial cells." (PMID 32669559, 2020). "In the body’s immune system, TNF-α plays a crucial role as an antitumor since it can trigger apoptosis and antiproliferation to fight cancer cells." (PMID 33369455, 2020). "The current clinical use of TNF is therefore limited to the treatment of advanced cancers in the limbs via isolated limb perfusion (ILP)." (PMID 31912630, 2020). "Tumor necrosis factor α (TNFα) is a pro-inflammatory cytokine whose expression is increased in a variety of cancers." (PMID 32391269, 2020). "These DEPs are involved in cancer transcriptional dysregulation, IgA production of intestinal immune network, TNF signaling pathway, IL-17 signaling pathway, toll-like receptor signaling pathway." (PMID 32799626, 2020). "Tumor necrosis factor-alpha (TNFα) is a cytokine that regulates various biological processes of cancer, including inflammation, cell proliferation and apoptosis, progression and metastasis, and chemoresistance." (PMID 32986377, 2020). "While these need to be addressed to confirm reproducibility of our observations, the finding of TNF-α inhibition occurred across all cancer types and using both in vitro and ex vivo cancer samples." (PMID 32552799, 2020). "The levels of inflammatory cytokines, such as IL-6 and TNF-α, increased in patients with poor PS and cancer cachexia." (PMID 32792640, 2020). "These include the IL-17 signaling pathway, the Jak-STAT signaling pathway, TNF signaling pathway, and transcriptional misregulation in cancer." (PMID 32962103, 2020). "TNF-α, a highly pro-inflammatory cytokine secreted by effector immune cells, is one of the cytotoxic effector proteins capable of inducing cancer cell apoptosis." (PMID 33322371, 2020). "Some of the cancer related inflammatory factors involved in the development of cancer are tumor necrosis factor, chemokines, inflammasomes, transcription factors, cytokines, infiltrating or circulating immune cells, and ROS." (PMID 32660101, 2020).
cancer (continued). "Individuals with various types of cancer (15 cases), diagnosed in local clinics and hospitals 1–3 years previously, showed salivary TNF protein levels which were 2–3 fold higher than healthy control group." (PMID 32019214, 2020). "In mice, carcinoma induces activation of myeloid cells via TLR2 to stimulate lung metastasis with expression of TNF-α." (PMID 32547964, 2020). "The obtained results showed that compound 1, 2, and 3 were capable of lowering NO, TNF-α, and IL-1β release and suppressed the growth and development of human carcinoma cell lines." (PMID 33302335, 2020). "On the other hand, TNF-α stimulates proliferation, survival, angiogenesis, and metastasis in most cancer cells that are resistant to TNF-α-induced cell death." (PMID 31766230, 2019). "The ROC analysis comparing patients with ICC to Ctrl HPV− revealed that five tested cancer biomarkers: TNFα, CYFRA 21-1, macrophage migration inhibitory factor (MIF), prolactin and SCF had AUC greater than 0.8." (PMID 31089160, 2019). "The TNF-α mRNA ISH signal was often seen in cancer cells with a branching appearance, i.e., cells that show initial outgrowth from the cohesive adenocarcinoma structure, whereas the front-runner budding cancer cells were often TNF-α mRNA negative." (PMID 30999696, 2019). "Our results showed that mechanical stresses produced by boiling histotripsy promote immunogenic cell death of cancer cells via TNF-induced necrosis signaling pathway." (PMID 31227775, 2019). "Given that ROS overproduction and antioxidant enzyme activities reduction play an important role in the inflammatory response in cancer cells, we measured the levels of cytokines as TNF-α and IL-6 within HCT 116 cells using ELISA test." (PMID 31269760, 2019). "A recent study has shown that most cancer cells are resistant to TNF-α-induced cell death, which is known to be involved with the overexpression of antiapoptotic outcomes and the survival of proteins leading to the inhibition of the apoptotic pathway." (PMID 31766230, 2019). "IL-1α and IL-1β are amongst the most prominent and potent inflammatory cytokines, together with TGFβ, TNFα, and IL-6, in the TME, and are implicated in cancer-related inflammation." (PMID 31557902, 2019). "The upregulation of WNT5A, which is linked to the epithelial mesenchymal transition (EMT) process and cancer progression, has also been shown to be induced by NF-κB signaling, as is the rapid transcriptional activation of TNF-α." (PMID 31164956, 2019). "We also found significant positive correlations between cancer‐related cytokine TNF‐α and (a) bcl‐2 (r > 0.1, P < 0.0001); (b) ΔNp63, c‐REL (r > 0.97, P < 0.0003); (c) WNT5A (r > 0.88, P < 0.01)." (PMID 31173474, 2019). "Overexpression of GSDME in cancer cells switched caspase-3-mediated apoptosis triggered by tumor necrosis factor (TNF) or chemotherapeutic agents to pyroptosis." (PMID 31492049, 2019). "After the boiling histotripsy exposure, cancer cells were mechanically fractionated and underwent cell death via TNF-induced necrosis." (PMID 31227775, 2019). "Inflammatory cytokines, such as interleukin-6 (IL-6), IL-1, and tumor necrosis factor-alpha (TNF-α), can promote cancer progression." (PMID 31766230, 2019). "The particular localization of the TNF-α mRNA expressing cells suggests a role in aggressive cancer cell invasion." (PMID 30999696, 2019). "TRAIL is a member of the tumor necrosis factor (TNF) family that came into the spotlight as a potential antitumor agent, as it is capable of inducing apoptosis selectively in transformed/cancer cells." (PMID 30805008, 2019). "Collectively, our results suggest that Pgp and endogenous TNF-α positively regulate cancer cell malignancy and contribute to changes in normal cell behavior through MP." (PMID 31137684, 2019). "Efforts to combine TNF agonists with other cancer therapies such as 17-allylamino-17-demethoxygeldanamycin (17AAG) have been tested in several human cancer cell lines in vitro." (PMID 32039025, 2019).
cancer (continued). "Various inflammatory cytokines from cancer cells, such as IL-1β and TNF-α, activate endothelial cells and promote leukostasis." (PMID 31434194, 2019). "Meanwhile, TNF-α has been suggested to confer anti-cancer properties and was also produced by plasma-polarized macrophages during the co-culture." (PMID 31216715, 2019). "Studies have shown that inflammatory factors (especially IL-6 and TNF-α) play an important role in the occurrence and development of cancer cachexia." (PMID 31788012, 2019). "TNFα‐CSG treatment in pre‐clinical cancer models attracts immune cells which in turn secrete a cocktail of proteases and degrade ECM locally." (PMID 31709774, 2019). "It was found that Coley′s toxin, which is a mixture of supernatants of Streptococcus pyogenes and Serratia marcescens cultures, was supposed to exhibit anti-cancer activity due to its ability to induce the release of tumor necrosis factor-α (TNF-α)." (PMID 32184862, 2019). "The FDA has approved TNF-α as an adjuvant therapy for cancer, but chronic administration of TNF-α for cancer treatment is still debated." (PMID 30871059, 2019). "Infections by P. gingivalis and F. nucleatum have been proven to cause cancer through pathways of MMP9 and upregulation of cytokines such as TNF-α, IL-1β, and IL-6." (PMID 31297102, 2019). "Initially investigated as a cancer therapeutic due to its ability to promote apoptotic cell death specifically of tumor cells, systemic TNF-α treatment has failed clinical trials as a solo cancer therapeutic due to unacceptable levels of toxicity." (PMID 31263060, 2019). "The possible connection of MADD to β-Catenin regulation stemmed from our previous studies wherein, we showed that MADD protects cells from TNFα mediated cytotoxicity in cancer cells by facilitating TNFα induced MAPK activation." (PMID 30760700, 2019). "Although TNF-α is involved in cancer progression, its more prominent pro-tumoral effects have been seen in angiogenesis and invasion of cancer cells." (PMID 31921870, 2019). "As one of potent mediators of inflammation, the tumor necrosis factor (TNF) family plays an important role in the process of immunoregulation and further contributes to cancer development." (PMID 30736740, 2019). "Although several anti-TNF therapies have been developed with different binding and pharmacokinetic profiles, TNF is used in current therapies to fight cancer, notwithstanding its toxicity." (PMID 31381571, 2019). "In order to evaluate the relationship between the anti-cancer effects of butein treatment and its inhibitory effect on TNFα-activated proinflammatory cytokines, a semi-quantitative analysis using human antibody arrays was performed." (PMID 31665136, 2019). "The combined staining revealed localization of miR-17 in the cancer cells as expected, and TNF-α mRNA was, in this case, mostly seen in CK-positive cancer cells located at the invasive front." (PMID 30999696, 2019). "In this study, we demonstrated that rTNF-α regulates Pgp and endogenous TNF-α expression in cancer cells." (PMID 31137684, 2019). "Whereas IFNγ and TNF are canonical pro-inflammatory cytokines, IL-2 has attained a more dichotomous role in cancer immunotherapy, with T cell stimulatory capacities on one hand and immunosuppressive characteristics on the other hand." (PMID 31195686, 2019). "The link between NF-κB signaling and many aspects of cancer has been well established for more than two decades, since it was first noted that NF-κB is capable of inhibiting TNF-α-induced apoptosis." (PMID 31561620, 2019). "One of the studied cytokines is TNF-α, however the exact biological role of it in cancer promotion is not fully understood." (PMID 31340751, 2019). "TNFα is highly expressed and is involved in many acute and chronic inflammatory diseases and cancer; it also induces many different signal transduction pathways that regulate cellular responses." (PMID 30818829, 2019).
cancer (continued). "First, primary tumors of Survivors were associated with anti-cancer signaling such as INF-α/-γ response and TNF-α signaling, compared with the recurrence groups." (PMID 31729458, 2019). "Human endothelial cells stimulated with microparticles obtained from cancer patients post-VEGFi treatment induced a significant increase in gene expression of pro-inflammatory markers including TNF-α, IL-6, MCP-1, iNOS, COX-2, and VCAM-1." (PMID 30753341, 2019). "Resveratrol inhibits TNF-α-induced migration and invasion of cancer cells through downregulation of NF-κB expression as well as its downstream molecules (uPA and uPAR)." (PMID 30791624, 2019). "As inflammation plays a key role in cancer progression and the microenvironment of cancer is controlled by inflammatory cells, previous studies have explored TNF-TNFRs interactions in cancer proliferation, metastasis and immune evasion." (PMID 31877663, 2019). "Similar to cancer, many of these factors including TNFα, IL-6, IL-1, LIF, activin A, and myostatin activate Akt in skeletal muscle cells while stimulating muscle protein loss." (PMID 31480237, 2019). "It has been proposed that this type of MDP delivery activates tumoricidal activity of macrophages by triggering the secretion of cytokines (IL‐1, IL‐6, and TNF‐α) and other soluble mediators leading to final eradication of cancer cells." (PMID 30548868, 2019). "Chronic incidence of TNF-α and IL-1β in tumors stimulate pro-tumoral effects in several cancers, showing that these two cytokines are potential targets for cancer therapy." (PMID 31665136, 2019). "We have also recently shown that macrophage-secreted TNF-α acts as a critical player for cancer cell death after cold plasma treatment." (PMID 31216715, 2019). "The observations in our study suggest that TNF-α also mediate an autocrine mechanism that contributes to cancer invasion." (PMID 30999696, 2019). "Then, neutralizing TNFα in the co-culture or pretreatment of cancer cells with anti-TNFR1 mAb significantly decreased the production of CCL2." (PMID 31780645, 2019). "These antitumor roles of CD4+ Th1 cells are mainly driven by the triad of cytokines, such as IFN-γ, TNF-α and IL-2.5,6 Furthermore, a clinical benefit associated with Th1-polarised signature in the TME has been reported in many human cancers." (PMID 31358938, 2019). "TNF-related apoptosis-inducing ligand (TRAIL) is a tumor necrosis factor (TNF) gene which possesses apoptosis-inducing activity against cancer cells in vivo and in vitro." (PMID 31540128, 2019). "Activated NK cells eliminate target cancer cells by either secreting perforin or granzyme or by apoptosis mediated through interaction of TNF, FasL, and TRAIL with corresponding death receptors." (PMID 31769418, 2019). "Pre-clinical studies suggest that TNFα plays a major role in cancer cachexia, above all in muscle wasting." (PMID 30764482, 2019). "Despite its role in the induction of apoptosis, most cancer cells show resistance to TNF-α-induced apoptosis." (PMID 30791624, 2019). "Among others, tumor necrosis factor-alpha (TNF-α) and interleukin-6 (IL-6) and IL-8 were found to play a crucial role in cancer cachexia contributing to muscle loss and lipid wasting by increasing protein breakdown and adipocyte lipolysis." (PMID 31717736, 2019). "We had previously reported a differentially overexpressed splice variant of IG20 gene, MADD (MAPK-activating Death Domain activating protein) in cancer cell survival in the context of TNFα signaling." (PMID 30760700, 2019). "Another report concluded that SSD enhances the anticancer potency of TNF-alpha by overcoming its undesirable response of activating NF-kappa B signaling in cancer cells." (PMID 31777595, 2019).
cancer (continued). "Over the last decade, increasing evidence has indicated that the cell fusion frequency in several kinds of cancers was enhanced by the pro-inflammatory cytokine TNF-α." (PMID 31266502, 2019). "KEGG enrichment analysis revealed that the potential targets of momordicoside G were significantly enriched in the “Pathways in cancer,” “TNF signaling pathway,” and “RIG-I-like receptor signaling pathway” terms." (PMID 30984004, 2019). "For example, TNFα and IL-6 trans-signaling induced by the cancer cells accelerates autophagy/mitophagy in skeletal muscle, hereby promoting cachexia." (PMID 31121959, 2019). "Cell migration is indeed an important aspect during carcinogenesis and metastasis of cancer cells, therefore this finding adds to growing evidence of the potential significance of TNF-α/Hippo signal crosstalk." (PMID 31083564, 2019). "TNFα is an important cytokine regulator of inflammatory and immune responses and has implications as an inducer of cancer-related fatigue." (PMID 30678249, 2019). "Owing to the production of soluble factors in cancer, such as interleukin-10 (IL-10), tumor necrotic factor (TNF), transforming growth factor (TGF)-β, and VEGF, the function and action of immune cells are blocked." (PMID 30871059, 2019). "Neutrophils, expressing the hepatocyte growth factor receptor c-MET, inhibit growth of several cancer types, through the release of tumor necrosis factor α (TNFα) and nitric oxide (NO)." (PMID 31461847, 2019). "First hopes in targeting a death receptor for cancer therapy became disillusioning when fulminant toxicity occurred in clinical trials of phase I and phase II testing recombinant TNF-α." (PMID 30935038, 2019). "TNF-α plays an important role in cancer cell proliferation by inducing the expression of proliferative proteins." (PMID 31540489, 2019). "Recently, we demonstrated that minocycline, a tetracycline antibiotic, successfully inhibited the TNF-α-induced fusion of MDA-MB-435 cancer cells with M13SV1 breast epithelial cells." (PMID 31266502, 2019). "Seven of these biomarkers (TNFα, sFasL, SCF, VEGF, leptin, prolactin, OPN) were also significantly elevated in the cancer-associated cluster compared to the high diversity/inflammation cluster (P ranging from 0.02 to <0.0001)." (PMID 31089160, 2019). "TNFα is a critical macrophage-produced mediator that elevates the production of CCL2 by multiple types of cancer cells." (PMID 31780645, 2019). "Gene expression studies performed by RT-qPCR of selected cancer biomarkers in tissue from biopsies of neoplastic tissue revealed that FaOH and FaDOH downregulated NF-κβ and its downstream inflammatory markers TNFα, IL-6, and COX-2." (PMID 31540047, 2019). "We also identified an auto-regulatory loop between TAMs and cancer cells driven by tumor necrosis factor alpha involving SIGLEC1 and CCL8, which is self-reinforcing through the production of CSF1." (PMID 30930117, 2019). "Inflammatory cytokines, such as tumor-necrosis factor-α (TNF-α), interleukin-6 (IL-6) and IL-8, are often upregulated and promote the invasive properties of cancer, such as angiogenesis and metastasis." (PMID 31439034, 2019). "Thereby the use of TNF-α in cancer therapy is limited to isolated limb perfusion (ILP) of advanced melanoma and soft tissue sarcoma." (PMID 31179236, 2019). "Two pathways; “TNF signaling pathway” and “Pathways in cancer” were common to all with TNF signaling pathway being most robustly enriched (Benjamini ≤0.05) in HBE cells and airway tissue, and “Pathways in cancer” showing Benjamini ≤0.05 in BEAS-2B cells." (PMID 30704470, 2019). "Co-localization of the TNF-α mRNA in the CK positive cells indicated that this potent pro-inflammatory cytokine is expressed in a small subset of cancer cells located at the invasive front." (PMID 30999696, 2019).